RNU1-125P (RNA, U1 small nuclear 125, pseudogene)
Gene: Small nuclear RNA gene on chromosome 16 (3,069,523 to 3,069,651, forward strand). Ensembl gene ENSG00000252561.
Homologues: Orthologues: chimpanzee U1 (99% identical), mouse Gm55070 (50% identical), guinea pig U1 (43% identical). Paralogues in human: RNU1-1 (67% identical), RNU1-14P (67% identical), RNU1-2 (67% identical), RNU1-27P (67% identical), RNU1-28P (67% identical), RNU1-3 (67% identical), RNU1-39P (67% identical), RNU1-4 (67% identical), RNVU1-18 (67% identical), RNVU1-29 (67% identical), RNVU1-7 (67% identical), U1 (67% identical), and 133 more.